MIR8060 (microRNA 8060)
Synonyms: hsa-mir-8060
Gene: MicroRNA gene on chromosome 3 (96,359,964 to 96,360,039, forward strand). Ensembl gene ENSG00000278103.
Homologues: Orthologues: chimpanzee MIR8060 (100% identical).